RN7SL455P (RNA, 7SL, cytoplasmic 455, pseudogene)
Gene: Miscellaneous RNA gene on chromosome 2 (43,904,412 to 43,904,693, forward strand). Ensembl gene ENSG00000264047.
Homologues: Orthologues: chimpanzee Metazoa_SRP (99% identical), macaque Metazoa_SRP (33% identical). Paralogues in human: Metazoa_SRP (85% identical), Metazoa_SRP (72% identical), RN7SL531P (71% identical), Metazoa_SRP (71% identical), RN7SL605P (70% identical), Metazoa_SRP (70% identical), Metazoa_SRP (69% identical), Metazoa_SRP (68% identical), Metazoa_SRP (67% identical), Metazoa_SRP (66% identical), Metazoa_SRP (65% identical), Metazoa_SRP (64% identical), and 704 more.